TNF (tumor necrosis factor)
Diseases named in the same sentence as TNF in open-access papers (continued):
Sharing a sentence is not in itself a finding about the gene and the disease.
injury (continued). "During various forms of CNS trauma, proinflammatory cytokines including TNF-α, IL-1, and interferon play a critical role in illness development, ultimately leading to decreased energy generation, cell death, and brain damage." (PMID 36593774, 2022). "LIG reduced MDA and TNF-α levels in I/R-induced renal injury mice by downregulating oxidative stress and apoptosis and reducing neutrophil infiltration." (PMID 34437444, 2021). "After TNF-α stimulation and nerve injury, JNK would be activated in spinal cord astrocytes, which is critical for the development and maintenance of neuropathic pain." (PMID 34899191, 2021). "The neuroinflammatory response, including the production of pro-inflammatory cytokines IL-6 and TNF-α, is also curbed by ketamine treatment following an insult in a traumatic brain injury model." (PMID 33672922, 2021). "In conclusion, we proposed that TNF-α-related cell death pathway involved in ConA-induced acute liver injury." (PMID 35006454, 2021). "Multiple studies have shown that TNF-α-triggered MAPK cascades mediate various cellular responses to cisplatin-induced kidney injury." (PMID 35186944, 2021). "One study reported the effectiveness of anti-TNFα antibody in the amelioration of DKD in Ins2Akita diabetic mice and protection from streptozocin-treated hyperglycemic kidney injury in another macrophage-specific TNFα-deficient mice model." (PMID 34045516, 2021). "Whereas most studies generally focus on the use of one cytokine, a few studies have used a combination of TNF-α, IL-6 and soluble IL-6 receptor (sIL-6R) to better simulate the inflammatory environment existing after knee trauma." (PMID 33671471, 2021). "Another finding of this study is that TNF-α pretreatment enhances the neuroprotective effect of hNPC transplantation after HI brain injury." (PMID 32403417, 2020). "RosA significantly reduced LPS-induced TNF-α, IL-6, and IL-1β production; RosA plays an anti-inflammatory effect on the acute lung injury in mice by inhibiting ERK/MAPK signaling in a dose-dependent manner." (PMID 32184728, 2020). "Previous studies have shown that ERK, JNK, and p38 are closely bound up with various inflammatory diseases, such as acute lung injury, and can be activated by LPS, TNF, and other irritants." (PMID 32005962, 2020). "Calcitriol, the active form of vitamin D, has been confirmed that it can reduce the infiltration of inflammatory cells and attenuate the elevation of TNF-α during LPS-induced acute lung injury in mice." (PMID 31919742, 2020). "It has been proved that the level of IL‐6 in serum and the secretion of cytokines, including IL‐1 β and TNF‐α, increase with the increase of cerebrospinal fluid after brain injury." (PMID 32533644, 2020). "HMGB1 has also been shown to drive the alveolar macrophage production of inflammatory factors, including IL-1β and TNF-α, thereby inducing acute lung injury." (PMID 31958320, 2020). "Among these mediators, TNF-α, the terminal effector in the pathogenesis of acute liver injury, initiates extensive hepatocyte apoptosis and massive hepatocyte necrosis, prompting the explosion of inflammation." (PMID 32158448, 2020). "When myocardial ischemia-reperfusion injury occurs, the expression of pro-inflammatory factors increased, mainly due to the increased release of TNF-α and IL-1β." (PMID 32116705, 2020). "Our results suggest some links between TNF-α-pretreated hNPC transplantation and neuroprotection and improved neurological functions after HI brain injury." (PMID 32403417, 2020). "The effects of TNF-α-hNPC and untreated hNPC transplantation on neurobehavioral deficits induced by HI brain injury were evaluated." (PMID 32403417, 2020). "In conclusion, these data revealed that MF exhibited significant protection against LPS/D-GalN-induced acute liver injury and alleviated TNF-α production through the inhibition of the TLR4/NF-κB signaling pathway." (PMID 32158448, 2020).
injury (continued). "More patients with liver injury had increased serum IL-2R, TNFα, ferritin, hsCRP, PCT, ESR, γ-GT, and LDH." (PMID 33026573, 2020). "During NP induced by nerve injury, the TNF-α action as recognized acts at different levels of the nervous system." (PMID 30755780, 2019). "The results also showed that white tea downregulated the expression of COX-2, iNOS, NF-κB, IL-1β, and TNF-α in mice with liver injury and upregulated the expression of IκB-α, thus alleviating liver injury by inhibiting oxidative stress." (PMID 30875793, 2019). "However, excessive and prolonged training with insufficient recovery might cause musculoskeletal trauma with increased production of proinflammatory cytokines such as TNF- α, IL-1β, and IL-6, which contributes to symptoms related to performance decrement and exercise-induced fatigue." (PMID 32082125, 2019). "Among these proinflammatory cytokines, TNF-α is capable of promoting tubular apoptosis after kidney injury, as neutralization of TNF-α leads to decreased renal IRI." (PMID 31179346, 2019). "Inflammatory cytokines such as TNF-α and IL-6 play essential roles in the pathogenesis of ConA-induced liver injury." (PMID 30622431, 2018). "In mice, levels of TNF-α, IL-1β, and IL-6 show an early rise (peaking at 2–4 h after aggression) in a lipopolysaccharide-induced lung injury model." (PMID 29515461, 2018). "PQ activates the NF-κB signaling pathway, resulting in the release of TNF-α, IL-1β, and IL-6 and leading to acute lung injury." (PMID 29566055, 2018). "We evaluated TNF-α, IL-6, and IL-1β, the major mediators in ConA-induced liver injury, and found that their expression was consistent with the extent of necrosis, apoptosis, and autophagy." (PMID 30116260, 2018). "For example, AM suppresses the in vitro secretion and gene transcription of TNF-α and IL-6 in the murine monocyte/macrophage cell line RAW 264.7 and also attenuates TNF-α and IL-1β production in an in vivo acute lung injury mouse model." (PMID 28299347, 2017). "In a prospective cohort clinical study, the number of CD14+ monocytes producing IL-12, tumor necrosis factor (TNF)-α, and IL-6 after lipopolysaccharide stimulation was 40% to 70% lower in trauma patients than in healthy control subjects." (PMID 29221433, 2017). "Our previous study found that salidroside attenuated serum IL-6 and TNF-α levels in LPS-induced acute lung injury." (PMID 29333216, 2017). "As elevated inflammatory cytokines are associated with fibrogenesis, we assessed the impact of TNF-α inhibition on ERG expression and SMAD3 activity by co-administration of the TNF-α antagonist etanercept in an acute CCL4-induced liver injury." (PMID 29026072, 2017). "Similar mechanisms of magnolol can also be found in LPS-induced acute lung injury mice models by inhibiting the tumor necrosis factor-alpha (TNF-α), IL-1β, phosphorylation of IκB-α and NF-κB, and expression of toll-like receptor 4 (TLR4)." (PMID 28726741, 2017). "Studies have confirmed that maresin 1 can suppress neutrophil infiltration and adhesion and reduce proinflammatory mediators such as TNF-α, IL-1β, and IL-6 in mice induced by acute lung injury." (PMID 28182085, 2017). "In our present data, serum TNF-alpha levels were significant decreased in ISO-induced heart injury mice after DRLE treatment." (PMID 27936072, 2016). "TNF signaling also plays a major role in the pathophysiology of lung diseases such as acute lung injury (ALI) and chronic obstructive pulmonary disease." (PMID 27435289, 2016). "Similar results were also observed in early reports that RAGE induced NF-κB activation and IL-1 and TNF-α production were dependent on p38 phosphorylation in diabetic glomerular injury." (PMID 27688824, 2016). "IL-6 and IL-12 have been reported to be key mediators of acute lung injury in mice while IFN-γ and TNF-α were associated with acute lung injury." (PMID 26136733, 2015).
injury (continued). "Elevated concentrations of proinflammatory cytokines, such as interleukin-1β (IL-1β), interleukin-6 (IL-6) and tumor necrosis factor-α (TNFα), are frequently detected in the brain, cord blood, and amniotic fluid of very preterm infants with brain injury." (PMID 25898410, 2015). "I3C was found to reduce cellular infiltration into the broncho-alveolar lavage fluid (BALF) of LPS-induced acute lung injury, while also decreasing proinflammatory cytokines, such as IL-6 and TNF-α, in the lungs." (PMID 25706292, 2015). "Several pro-inflammatory cytokines such as tumor necrosis factor-α (TNF-α) are elevated in acute myocardial injury and infarction." (PMID 26173590, 2015). "It is known that an increase in the level of pro-inflammatory cytokines, including TNF-α and IL-6, is an early feature of acute lung injury induced by clinical and experimental I/R." (PMID 24345905, 2014). "Asiaticoside reduced the content of IL-6 and TNF-alpha in a dose-dependent manner in acute lung injury." (PMID 24667059, 2014). "This interaction of TLR4 and MyD88 triggers the downstream signaling cascade leading to the activation of the nuclear factor κB (NF-κB) pathway, further releasing inflammatory cytokines such as TNF-α and IL-6, which, in turn, can result in liver injury." (PMID 25328713, 2014). "We found that the upregulation of TNF-α expression was accompanied by the upregulation of the Fas genes in CCl4-induced liver injury." (PMID 23374533, 2013). "Our previous studies showed that anti-TNF antibodies or soluble TNFRp55 were unable to block the TNF/TNFRp55 pathway, and reduce the mortality of animals with acute liver injury." (PMID 23874752, 2013). "Blast limb trauma triggered the local and system inflammatory response, characterized by release of cytokines, such as TNF-α and IL-6, and those cytokines play important roles in the early phase of acute lung injury." (PMID 23527096, 2013). "Previous reports showed that M1 monocytes activated by brain inflammation or brain injury secrete the pro-inflammatory cytokines TNF-α and IL-1β." (PMID 24303068, 2013). "After nerve injury, TNF-α is upregulated in activated cells of the central and peripheral nervous systems." (PMID 23469058, 2013). "It has been shown that a concussion does in fact cause an increase in TNF-α secretion; however, it is uncertain how the increase in TNF-α differs between a concussion and a more severe brain injury." (PMID 23248582, 2012). "Reports indicate either exacerbation or amelioration of pathological conditions in the brain during TNF-α treatment, including experimentally induced brain trauma and a murine model of multiple sclerosis." (PMID 19490629, 2009). "It has been suggested before that nerve injury and TNF-induced pain-related behaviour is partly dependent upon peripheral prostaglandins." (PMID 17971769, 2007). "Scherbel and colleagues were the first to provide evidence of beneficial effects of TNF in the later phase (i.e. 4 weeks) after traumatic brain injury, based on studies in TNF-/- mice subjected to controlled cortical impact brain injury." (PMID 15285802, 2004). "Conversely, skin injury or chronic dermatoses can release inflammatory cytokines, including IL-1β and tumor necrosis factor-alpha (TNF-α), which may impair intestinal barrier integrity and disrupt the gut microbial composition." (PMID 41010451, 2025). "While serum TNF-α measurement would provide mechanistic confirmation, our genetic approach offers superior predictive utility by identifying patients requiring intensive monitoring before irreversible kidney injury occurs." (PMID 40724987, 2025). "Moreover, glycyrrhizin has been shown to reduce mitochondrial damage by inhibiting neuronal nitric oxide synthase upregulation in acetaminophen-induced liver injury and to reduce liver injury by inhibiting tissue necrosis factor (TNF)α-dependent apoptosis." (PMID 40046366, 2025).
injury (continued). "Similarly, Sauer, Peukert have reported that MXF reduced levels of TNF-α and IL-6 in a mouse model of acute lung injury." (PMID 40327662, 2025). "TNF, interleukin (IL)-1, and IL-23, among the inflammatory cytokines generated by macrophages, have been demonstrated to have a substantial role in brain injury and neural dysfunctions." (PMID 40809171, 2025). "In addition, IL-2 can synergistically promote vascular leakage with TNF-α in superantigen or pathogen-induced acute lung injury." (PMID 38967887, 2024). "In addition, protocatechuic acid demonstrated protection against the development of LPS-induced acute lung injury in mice by lowering the levels of TNF-α and IL-1β." (PMID 39129025, 2024). "In addition, type-I IFN produced from liver parenchymal cells in an IRF3-dependent manner was protective in alcoholic-induced liver injury by increasing IL-10 production and decreasing TNF-α production in NPCs." (PMID 38539789, 2024). "TNF-α is a proinflammatory cytokine produced by macrophages and secreted by neutrophil granulocytes at sites of injury and is involved in the inflammatory cascade of acute lung injury." (PMID 36657981, 2023). "TNF-α is one of the pro-inflammatory cytokines that is commonly upregulated in acute lung injury." (PMID 37342247, 2023). "On the other hand, IL-1β/IFN-γ/TNFα-preconditioned BM-MSCs reduced structural abnormalities and inflammation in lungs and restored oxygenation and improved lung compliance in experimental ventilator-induced lung injury." (PMID 37007034, 2023). "Dexmedetomidine-mediated effects on CAP have been demonstrated to alleviate renal ischaemia–reperfusion injury and LPS-induced acute lung injury in rodent models, decreasing inflammatory mediators (amongst others interleukin [IL]-1β, IL-6, and tumour necrosis factor-alpha [TNF-α])." (PMID 37588789, 2022). "Aerobic exercise can also modulate the inflammatory/anti-inflammatory and oxidative/antioxidative balance in the early stage of LPS-induced lung injury, which leads to a decrease in the release of inflammatory mediators such as TNF-α, IL-6, IL-10, IL-1β, IL-17, GM-CSF, and CXCL1/KC." (PMID 36456896, 2022). "Importantly, decreased serum level of TNFα and Il-1β in SCI patients after 9 h following injury correlated with the American Spinal Injury Association’s (ASIA) impairment scale (AIS) improvement." (PMID 36289607, 2022). "In addition, various proinflammatory cytokines, including tumor necrosis factor (TNF)-α, interleukin (IL)-1β, and IL-6, can trigger and amplify liver destruction and acute liver injury." (PMID 35345558, 2022). "Likewise, L. plantarum C88 downregulated the expression of NFκB in a LPS/GalN-induced acute liver injury mouse model, which decreased the levels of TNF-α, IL-6, and IL-12 in liver." (PMID 35903291, 2022). "Intraperitoneal injection of galangin can remarkably inhibit the LPS-induced synthesis of IL-6 and TNF-α, the change in lung tissue dry/wet weight ratio, and the disruption of lung tissue structure, improving the survival rate of rats with inflammatory lung injury." (PMID 36072628, 2022). "On the other hand, another study reported that epigallocatechin gallate (EGCG) could attenuate lipopolysaccharide-stimulated acute lung injury in mice and restrained the liberation of inflammatory cytokines TNF-α, IL-1β, and IL-6." (PMID 36290242, 2022). "Conversely, EGFR activation has been shown to suppress epithelial cell apoptosis in an LPS model of acute lung injury, and EGFR inhibition with a tyrosine kinase inhibitor promoted airway epithelial cell apoptosis in a tumor necrosis factor- (TNF-) induced model of acute lung injury." (PMID 36193076, 2022). "Moreover, it can inhibit C. albicans-induced macrophage stimulation (reduced activity of TLR-2, and TNF-α expression), and exhibits antifungal and anti-inflammatory action in a lung injury mouse model." (PMID 36551434, 2022).
injury (continued). "Moreover, TA was found to inhibit inflammatory response and apoptosis through attenuation of TNF-α, IL-1β, IL-6, Bax, Bcl-2, and caspase-3 in CCl4-induced liver injury in mice." (PMID 36358896, 2022). "TNF-α as a stimulus in vivo can mediate endothelial activation such as aortic endothelial injury." (PMID 34679642, 2021). "Captopril has been reported to decrease the level of TNFα, reduce alveolar wall thickening and neutrophil infiltration in rats with induced acute lung injury." (PMID 34768805, 2021). "A previous study reported that baicalin could diminish levels of pro-inflammatory mediators, TNF-α, IL-6 and IL-1β, in acute lung injury, functioning as a potential therapeutic candidate, which was largely consistent with the observations of our study." (PMID 34053448, 2021). "Moreover, TNF-α stimulates the activation and aggregation of neutrophils, which also plays an essential role in acute lung injury." (PMID 34774051, 2021). "Studies have shown that the CM of bone marrow mesenchymal stem cells (BMSCs) reduced the serum concentrations of TNF-α, IL-1β and IL-6; in contrast, the level of the anti-inflammatory cytokine IL-10 significantly increased in rats with radiation-induced liver injury." (PMID 33781342, 2021). "Because TNF-α is a key mediator in LPS/D-GalN-induced acute liver injury, we determined whether C14-Tri-LAN-Gly pretreatment diminished TNF-α production." (PMID 33746949, 2021). "Thus, TNF-α-pretreated hNPC-derived CX3CL1 play an important role in improving the neuroprotective effect in mice after HI brain injury by regulating the CX3CL1–CX3CR1 axis." (PMID 32403417, 2020). "Our results indicate that the neuroprotective effects of TNF-α-hNPCs in HI brain injury could be provided by stimulation of microglial CX3CR1 expression, as well as direct release of CX3CL1." (PMID 32403417, 2020). "After confirmation of the critical role of TNF-α in endotoxin-induced acute liver injury, we attempted to determine whether MF affected LPS-induced TNF-α production." (PMID 32158448, 2020). "The abrogation of TNF-α by MF pretreatment significantly retarded the progression of fulminant hepatic damage, which was a critical contribution to the mechanism of MF against acute liver injury." (PMID 32158448, 2020). "Our results reveal that TNF-α pretreatment improved the viability of hNPCs in HI brain injury." (PMID 32403417, 2020). "To investigate whether the neutrophil recruitment we observed in the CLEC-2 deficient mice was TNF-α dependent we used etanercept to inhibit TNF-α prior to induction of liver injury." (PMID 32321925, 2020). "Furthermore, NAP effectively suppressed TNF and IL-6 secretion in murine macrophages in vitro and of TNF in head trauma in vivo." (PMID 32466564, 2020). "Sesamol also reduced inflammatory cell secretions of TNF-α and IL-6, promoted superoxide dismutase expression to increase antioxidation effects, and reduced neutrophil infiltration in a rat model of LPS-induced acute lung injury." (PMID 32244835, 2020). "A previous study indicated that L-TAMS attenuated vincristine-induced allodynia via inhibition of TNF-α/NF-κB signaling in the SDH, and could restore memory deficits in spare nerve injury (SNI) rats through inhibition of TNF-α at a hippocampal level." (PMID 32241292, 2020). "In keeping with those findings, KC depletion could also abolish the protection of MF on LPS/D-GalN-mediated acute liver injury; adoptive transfer of KCs restored the protective effect of MF on LPS/D-GalN-mediated acute liver injury and TNF-α production." (PMID 32158448, 2020). "Compared with the septic group treated with antibiotic alone, concentrations of BUN (biochemical markers of kidney damage) and GOT (liver injury) in the serum, and serum TNF-α were also significantly reduced by the treatment with antibiotic combined with rhDNase." (PMID 30961634, 2019).